PARP9 (poly(ADP-ribose) polymerase family member 9)
Diseases named in the same sentence as PARP9 in open-access papers (continued):
Sharing a sentence is not in itself a finding about the gene and the disease.
cancer (12 papers, 2015 to 2025). A tumor composed of atypical neoplastic, often pleomorphic cells that invade other tissues. "Although PARP9 lacks enzymatic activity typical of other PARPs, its aberrant expression is linked to metastasis and drug resistance in various malignant tumors." (PMID 39739965, 2024). "We elucidated the mechanism by which PARP9 influenced the proliferation of challenging cancers both in vitro and in vivo." (PMID 41357999, 2025). "This study aimed to characterise the interactions and structural requirements of the complex of PARP9/DTX3L and PARP14 which is implicated in survival of several cancer cell types." (PMID 38182103, 2024). "The overexpression of the PARP9:DTX3L complex is observed in various cancers such as prostate and breast cancers, indicating its promoting role in the growth of cancer cells." (PMID 38000390, 2024). "To investigate the role of PARP9 in GC, we initially assessed its expression across various malignant tumors using the online database GEPIA." (PMID 39739965, 2024). "•PARP9 and DTX3L regulate PARP14 protein levels therefore depleting PARP9, DTX3L or PARP14 mRNA results in loss of PARP14 protein and a reduction in cancer cell survival through a loss of proliferation and increase in apoptosis." (PMID 38182103, 2024). "•PARP9 and PARP14 are lesser studied ADP-ribosyltransferases implicated in cancer cell survival." (PMID 38182103, 2024). "Since cancer cell survival was not dependent on PARP14 catalytic activity we postulate that PARP9/DTX3L regulates PARP14 expression and activity to promote proliferation and anti-apoptosis." (PMID 38182103, 2024). "Altogether, these preliminary findings suggest that the expression of PARP9, PARP12, PARP13 and PARP14 in irradiated cells is reliant on 3-dimensional cellular microenvironment or cell type, and the PARP expression pattern may be specific to cancer cells." (PMID 40646573, 2025). "Currently, there is no consolidated data on how PARP9, PARP12, PARP13 and PARP14 affect the response to ionizing radiation in cancer cells." (PMID 40646573, 2025).
bacterial infections (1 paper, 2023). "The current lack of knowledge about the molecular identity of bacterial cell wall components that are targets of the PARP9 complex limits our understanding of why PARP9 has an opposite role in viral and bacterial infections." (PMID 37200107, 2023).
cardiac diseases (1 paper, 2024). "In addition, since fibrotic and inflammatory processes are associated with the etiology and development of various heart diseases, the role of PARP9 in fibrosis and inflammation suggests it could be a promising therapeutic target for managing cardiac diseases." (PMID 39213416, 2024).
vascular disorder (1 paper, 2021). A general term used to describe any disease affecting blood vessels]. "Furthermore, in infected macrophages, activation by PARP9 and PARP14 may be hijacked by NSP3’s erasure of ADPr, potentially contributing to the vascular disorders seen in COVID‐19." (PMID 34519429, 2021).
PARP9 also shares sentences with these, for which no sentence is quoted: metastatic prostate carcinoma (4 papers); pulmonary TB (3); prostate tumors (2); atherosclerosis (1); autoimmune hemolytic anemia (1); brain tumors (1); breast tumors (1); cardiac hypertrophy (1); cardiovascular diseases (1); central nervous system diseases (1); cervical adenocarcinoma (1); cervical squamous cell carcinoma (1); cervical tumors (1); fibrosarcoma (1); heart failure (1); hepatocellular carcinoma (1); influenza (1); leukopenia (1); lung disease (1); lupus (1); macrophage activation syndrome (1); Moyamoya disease (1); multiple myeloma (1); myocarditis (1); non-Hodgkin lymphoma (1); renal carcinoma (1); renal cell carcinoma (1); respiratory failure (1); Sjögren’s syndrome (1); stomach adenocarcinoma (1).
A further 1 disease shares a sentence with PARP9 in 1 paper.